TUBBP1 (tubulin beta pseudogene 1)
Gene: Transcribed processed pseudogene on chromosome 8 (30,352,008 to 30,353,342, forward strand). Ensembl gene ENSG00000127589.
Diseases named in the same sentence as TUBBP1 in open-access papers:
TUBBP1 is named in the same sentence as 2 diseases in open-access papers, as found by Europe PMC text mining. Sharing a sentence is not in itself a finding about the gene and the disease. The quoted sentences say what the papers report.
melanoma (1 paper, 2024). A malignant, usually aggressive tumor composed of atypical, neoplastic melanocytes. "Indeed, all genes associated with nevus count or cutaneous nevi in cluster 6 (MTAP, TUBBP1, PLA2G6, ERVFRD.3, TMEM184B, BAIAP2L2) were only associated with melanoma." (PMID 38308491, 2024).
TUBBP1 also shares sentences with these, for which no sentence is quoted: nevus (1 paper).